POLR3H (RNA polymerase III subunit H)
Description:
DNA-dependent RNA polymerase catalyzes the transcription of DNA into RNA using the four ribonucleoside triphosphates as substrates. Specific peripheric component of RNA polymerase III (Pol III) which synthesizes small non-coding RNAs including 5S rRNA, snRNAs, tRNAs and miRNAs from at least 500 distinct genomic loci. With CRCP/RPC9 forms a mobile stalk that protrudes from Pol III core and functions primarily in transcription initiation (By similarity). Pol III plays a key role in sensing and limiting infection by intracellular bacteria and DNA viruses. Acts as nuclear and cytosolic DNA sensor involved in innate immune response. Can sense non-self dsDNA that serves as template for transcription into dsRNA. The non-self RNA polymerase III transcripts, such as Epstein-Barr virus-encoded RNAs (EBERs) induce type I interferon and NF-kappa-B through the RIG-I pathway.
Synonyms: RPC22.9; KIAA1665; RPC8; C25
Tractability: Small molecule: a structure with a bound ligand is known. PROTAC: ubiquitination databases record sites on it; its protein half-life has been measured.
Gene: Protein-coding gene on chromosome 22 (41,525,799 to 41,544,606, reverse strand). Ensembl gene ENSG00000100413.
Subcellular location: Nucleus
Subcellular location (Human Protein Atlas): Nucleoplasm; Centrosome; Vesicles
Pathways (Reactome):
Gene expression (Transcription): RNA Polymerase III Abortive And Retractive Initiation; RNA Polymerase III Chain Elongation; RNA Polymerase III Transcription Initiation From Type 1 Promoter; RNA Polymerase III Transcription Initiation From Type 2 Promoter; RNA Polymerase III Transcription Initiation From Type 3 Promoter; RNA Polymerase III Transcription Termination
Immune System: Cytosolic sensors of pathogen-associated DNA
Gene Ontology:
Molecular function: DNA-directed RNA polymerase activity; protein binding; DNA binding
Biological process: nucleobase-containing compound metabolic process; termination of RNA polymerase III transcription; transcription by RNA polymerase III; transcription initiation at RNA polymerase III promoter; DNA-templated transcription; DNA-templated transcription initiation
Cellular component: centrosome; nucleoplasm; nucleus; RNA polymerase III complex; cytosol; DNA-directed RNA polymerase complex
Genetic constraint (gnomAD): Loss-of-function variants: 14 observed, 23.36 expected, observed/expected ratio (o/e) 0.6, 90% interval 0.4 to 0.94. The upper end of that interval is the gene's LOEUF score, 0.94, which puts it in group 3 of 6, group 1 being the genes least tolerant of losing a copy. Missense variants: 271 observed, 271.84 expected, observed/expected ratio (o/e) 1, 90% interval 0.9 to 1.1. Synonymous variants: 128 observed, 108.17 expected, observed/expected ratio (o/e) 1.18, 90% interval 1.02 to 1.37.
Homologues: Orthologues: chimpanzee POLR3H (100% identical), macaque POLR3H (99% identical), mouse Polr3h (98% identical), rat Polr3h (98% identical), dog POLR3H (97% identical), pig POLR3H (96% identical), guinea pig POLR3H (93% identical), tropical clawed frog polr3h (89% identical), zebrafish polr3h (81% identical), rabbit POLR3H (68% identical), Drosophila melanogaster Polr3H (58% identical), Caenorhabditis elegans rpc-25 (39% identical). Paralogues in human: POLR1F (23% identical), POLR2G (14% identical).
Diseases named in the same sentence as POLR3H in open-access papers:
POLR3H is named in the same sentence as 11 diseases in open-access papers, as found by Europe PMC text mining. Sharing a sentence is not in itself a finding about the gene and the disease. The quoted sentences say what the papers report.
ovarian carcinoma (1 paper, 2022). A malignant neoplasm originating from the surface ovarian epithelium. "In our study, we found the signature-related genes such as AXL, FZD5, POLR3H, and MED1 were related to the immune cell expressions in ovarian cancer." (PMID 35769811, 2022). "However, no related researches of SLC30A8 and POLR3H have been studied in ovarian cancer." (PMID 35769811, 2022).
primary ovarian insufficiency (1 paper, 2021). "A mutation in POLR3H was recently found to cause primary ovarian failure and this phenotype was well-recapitulated in whole-body knock-in mice homozygous for the POLR3H Asp50Gly mutation." (PMID 34395528, 2021). "Finally, a homozygous variant in POLR3H has been associated with primary ovarian insufficiency." (PMID 34395528, 2021).
pulmonary fibrosis (1 paper, 2023). Chronic progressive interstitial lung disorder characterized by the replacement of the lung tissue by connective tissue, leading to progressive dyspnea, respiratory failure, or right heart failure. "According to the results of qRT-PCR, the expression levels of ENPP3, PDE7B, and ENTPD1 were elevated, while the expression levels of PNMT, GPX3, and POLR3H were decreased in the lung tissues of bleomycin-induced pulmonary fibrosis mice compared with the sham group." (PMID 36923791, 2023).
cancer (1 paper, 2013). A tumor composed of atypical neoplastic, often pleomorphic cells that invade other tissues. "The POLR3H gene codes for the polymerase (RNA) III (DNA-directed) polypeptide H. RNA polymerase (pol) III synthesizes several products required for protein synthesis, and there have been detected high rates of pol III transcription in several cancers (reviewed in 56)." (PMID 23634293, 2013).
POLR3H also shares sentences with these, for which no sentence is quoted: asthma (1 paper); Autoimmunity (1); depression (1); glioma (1); head and neck cancer (1); infection (1); tumor (1).